GFPT1 (glutamine--fructose-6-phosphate transaminase 1)
Description:
Rate-limiting enzyme of the hexosamine biosynthetic pathway (HBP) that catalyzes the formation of glucosamine-6-phosphate from fructose-6-phosphate and glutamine, thereby controlling the flux of glucose into this pathway. Inhibited by UDP-N-acetylglucosamine (UDP-GlcNAc) through a feedback loop. Fine-tunes the metabolic fluctuations of UDP-GlcNAc and its impacts on hyaluronan synthesis during tissue remodeling. Via control of the HPB, regulates the availability of precursors for N- and O-linked protein glycosylation and modulates peripheral clock oscillation (By similarity).
Synonyms: GFAT 1; GFAT1; GFAT; GFPT; GFA; CMS12; CMSTA1; GFAT1m; GFPT1L; MSLG
Tractability: Small molecule: a structure with a bound ligand is known; it has a binding pocket of medium quality; it belongs to a druggable protein family. PROTAC: ubiquitination databases record sites on it; its protein half-life has been measured; a small molecule that binds it is known.
Target class: Enzyme; Transferase
Gene: Protein-coding gene on chromosome 2 (69,319,780 to 69,387,281, reverse strand). Ensembl gene ENSG00000198380.
Subcellular location (Human Protein Atlas): Nucleoli; Nucleoplasm; Nucleoli fibrillar center
Pathways (Reactome):
Cellular responses to stimuli: XBP1(S) activates chaperone genes
Disease: Defective GFPT1 causes CMSTA1
Metabolism of proteins: Synthesis of UDP-N-acetyl-glucosamine
Gene Ontology:
Molecular function: glutamine-fructose-6-phosphate transaminase (isomerizing) activity; protein binding; carbohydrate derivative binding
Biological process: fructose 6-phosphate metabolic process; UDP-N-acetylglucosamine biosynthetic process; circadian regulation of gene expression; energy reserve metabolic process; carbohydrate derivative biosynthetic process; carbohydrate derivative metabolic process
Cellular component: extracellular exosome; cytosol
Genetic constraint (gnomAD): Loss-of-function variants: 17 observed, 35.62 expected, observed/expected ratio (o/e) 0.48, 90% interval 0.33 to 0.72. The upper end of that interval is the gene's LOEUF score, 0.72, which puts it in group 2 of 6, group 1 being the genes least tolerant of losing a copy. Missense variants: 194 observed, 445.81 expected, observed/expected ratio (o/e) 0.44, 90% interval 0.39 to 0.49. Synonymous variants: 134 observed, 146.86 expected, observed/expected ratio (o/e) 0.91, 90% interval 0.79 to 1.05.
Gene-disease validity (ClinGen):
ClinGen rates the evidence that GFPT1 causes each of these diseases.
congenital myasthenic syndrome 12 (autosomal recessive): Definitive.
Homologues: Orthologues: chimpanzee GFPT1 (100% identical), dog GFPT1 (99% identical), guinea pig GFPT1 (98% identical), pig GFPT1 (98% identical), macaque GFPT1 (97% identical), mouse Gfpt1 (97% identical), rat Gfpt1 (96% identical), rabbit GFPT1 (92% identical), tropical clawed frog gfpt1 (90% identical), zebrafish gfpt1 (87% identical). Paralogues in human: GFPT2 (78% identical).
Diseases named in the same sentence as GFPT1 in open-access papers:
GFPT1 is named in the same sentence as 93 diseases in open-access papers, as found by Europe PMC text mining. Sharing a sentence is not in itself a finding about the gene and the disease. The quoted sentences say what the papers report.
congenital myasthenic syndrome (20 papers, 2015 to 2025). Congenital myasthenic syndrome (CMS) is a group of genetic disorders of impaired neuromuscular transmission at the motor endplate characterized by fatigable muscle weakness. "Mutations in GFPT1 are associated with congenital myasthenic syndrome, a hereditary neuromuscular junction disorder, while gain-of-function mutations in GFPT1 have been linked to extended lifespan in C.elegans." (PMID 40830088, 2025). "The physiological relevance of GFPT1 is further underscored by its critical role in neuromuscular junction function, its association with congenital myasthenic syndromes, the presence of a muscle-specific isoform, and its essentiality for embryonic viability." (PMID 40830088, 2025). "To conclude, congenital myasthenic syndrome is a rare genetically inherited disorder, especially caused by the GFPT1 mutation." (PMID 39559672, 2024). "Mutations in GFPT1 and other genes downstream of this pathway cause congenital myasthenic syndrome (CMS) characterized by fatigable muscle weakness owing to impaired neurotransmission." (PMID 29905857, 2018). "For this analysis, we used two normal hiPSC lines (201B7 and 454E2) and two hiPSC lines derived from a patient with congenital myasthenic syndrome (CMS) due to a GFPT1 mutation (GFPT1 #3 and GFPT1 #8)." (PMID 29700358, 2018). "It has been reported that GFPT1 mutations lead to a distinct sub-class of congenital myasthenic syndromes (CMS) termed “limb-girdle CMS with tubular aggregates”." (PMID 26501342, 2015). "For instance, anomalies in PHETA1/2 have been associated with abnormal bone formation resulting in craniofacial defects, HAGH has been associated with skin, bone and joint infections in Yaws disease and mutations in GFPT1 have been associated with muscle weakness in congenital myasthenic syndrome." (PMID 34868271, 2021). "Thirteen unrelated families with autosomal recessive congenital myasthenic syndromes (CMS) have been described to have eighteen different biallelic mutations of Gfpt1." (PMID 37107691, 2023). "GFPT1-related congenital myasthenic syndrome (CMS) is a rare, autosomal recessive disorder that impairs neuromuscular transmission due to defective glycosylation of the neuromuscular junction." (PMID 41323224, 2025). "Pathogenic variants in GFPT1, encoding a key enzyme to synthesize UDP-N-acetylglucosamine (UDP-GlcNAc), cause congenital myasthenic syndrome (CMS)." (PMID 38903011, 2024). "In some cases, treatments such as acetylcholinesterase inhibitors may be considered, particularly in patients with pathogenic variants in congenital myasthenia genes (CHRNA1, CHRND, DPAGT1, and GFPT1)." (PMID 38982518, 2024). "Moreover, four families with CM carried pathogenic variants in GFPT1, CHRNA1, or CHRND, all three previously associated with congenital myasthenia often involving muscle weakness similar to CM." (PMID 38982518, 2024). "The underlying myopathic changes observed in GFPT1-related congenital myasthenic syndrome might also contribute to the lack of significant MGFA improvement, further emphasizing that this scale may not be the most appropriate tool to capture treatment effects in this scenario." (PMID 41323224, 2025).
pancreatic cancer (16 papers, 2016 to 2026). "As one of the first rate-limiting enzymes in HBP, GFPT1 overexpression is associated with a poor prognosis in prostate cancer, colon cancer, and pancreatic cancer." (PMID 36158580, 2022). "Moreover, polymorphisms of GFPT1 is significantly associated with the risk and overall survival in pancreatic cancer." (PMID 27509259, 2016). "Even though our report is the first demonstrating that upregulation of FASN increases the expression of GFPT1, other studies have demonstrated the oncogenic role of GFPT1 in cervical cancers, lung cancers and pancreatic cancers." (PMID 38732103, 2024). "For example, GFPT1 was upregulated in prostate, colon and pancreatic cancers, but downregulated in gastric cancer." (PMID 36158580, 2022). "To investigate the role of GFPT1 in pancreatic tumorigenesis, we examined the mRNA expression levels of GFPT1 in pancreatic tumor and normal tissues by analyzing GEO, TCGA, and GTEx dataset analyses." (PMID 33517899, 2021). "The expression of GFPT1 is highly upregulated in many cancers like pancreatic cancer compared to the normal tissue, since it can generate the uridine diphosphate N-acetylglucosamine (UDP-GlcNAc) to keep the level of glycosylated proteins and regulate the function of proteins." (PMID 32161720, 2020). "In addition, the rate-limiting enzyme of HBP, glutamine:fructose-6-phosphate amidotransferase-1 (GFPT1), is upregulated in pancreatic cancer cells." (PMID 32122374, 2020). "In addition, targeting GFPT1 by DON blocked the PCK1-loss induced O-GlcNAclyation and liver cancer aggressiveness, and enhanced anti-PD-1 immunotherapy effects in pancreatic cancer." (PMID 36158580, 2022). "Targeting tumor-intrinsic hexosamine biosynthesis by direct inhibition of GFPT1/2 by a small molecule glutamine analog (6-diazo-5-oxo-l-norleucine, DON) was recently shown to sensitize pancreatic cancer to anti-PD1 therapy and to result in tumor regression and prolonged survival." (PMID 33941787, 2021).
lung carcinoma (9 papers, 2022 to 2025). "Interleukin-8-induced CSC development in colon and lung cancer cells relies on GFPT1-mediated O-GlcNAc modifications, demonstrating the critical involvement of the HBP pathway in cancer stemness." (PMID 40830088, 2025). "GFPT1 overexpression also results in increased O-GlcNAcylation and regulates stem-like properties in colon and lung cancer cells." (PMID 38732103, 2024). "Likewise, GFPT1 stabilizes PD-L1 via O-GlcNAcylation, which promotes IFNγ-induced PD-L1 activation and reduces T-cell and NK-cell efficacy against lung cancer cells." (PMID 40830088, 2025). "GFPT1 protein levels were elevated in breast cancer, colon cancer, ovarian cancer, clear cell RCC, uterine corpus endometrial carcinoma, lung cancer, glioblastoma, and liver cancer tissues compared to normal tissues." (PMID 39664728, 2024). "The expression of GFPT2, an isoenzyme of GFPT1, is specifically induced in KRAS/LKB1 combined mutant lung cancer cells, and promotes tumorigenicity by enhancing glucose influx into HBP." (PMID 36158580, 2022). "Specifically, GFPT1 interacts with and glutamylates TAB1 (Transforming Growth Factor-β-Activated Kinase 1 Binding Protein 1), thereby promoting the recruitment and activation of p38 MAPK to support lung cancer cell survival under conditions of glucose deprivation." (PMID 40830088, 2025).
breast carcinoma (6 papers, 2015 to 2024). "Further analysis using TIMER2.0 demonstrated a robust association between GFPT1 expression and M2 macrophage infiltration in breast cancer tissues." (PMID 39664728, 2024). "In conclusion, GFPT1 serves as an independent prognostic marker in breast cancer patients, significantly associated with poorer survival outcomes." (PMID 39664728, 2024). "Elevated GFPT1 expression was linked to advanced-stage breast cancer and identified as an independent prognostic marker for overall survival (OS)." (PMID 39664728, 2024). "Significant risk factors for OS in breast cancer patients from the TCGA cohort included age (p = 1.2E-03), cancer stage (p = 1.6E-05), lymph node stage (p = 6.6E-07), distant metastasis stage (p = 0.005), and GFPT1 expression (p = 1.5E-04)." (PMID 39664728, 2024). "In the TCGA cohort, elevated GFPT1 expression in tumor tissues was correlated with poorer survival outcomes in breast cancer patients." (PMID 39664728, 2024). "Future research should focus on validating these findings in clinical settings and elucidating the precise mechanisms by which GFPT1 regulates oncogenic pathways, immune cell infiltration, and chemotherapy resistance in breast cancer." (PMID 39664728, 2024). "Our in vitro experiments further emphasize the clinical importance of GFPT1, as silencing its expression significantly impaired breast cancer cell viability, migration, and survival, while GFPT1 overexpression enhanced these properties." (PMID 39664728, 2024). "Overall, these results suggest that suppressing GFPT1 expression promotes apoptosis and necrosis, thereby hindering the growth of breast cancer cells." (PMID 39664728, 2024). "GFPT1 has been shown to promote breast cancer progression and immune escape through O-glycosylation-modified PD-L1, highlighting its potential role in tumor immune evasion mechanism." (PMID 39664728, 2024). "Our results demonstrated a decrease in GFPT1 protein expression in the breast carcinoma cell lines (MCF-7, MB-MDA-231, and T47D) compared to the MCF-10A cell line." (PMID 39664728, 2024). "This study utilized integrated data from The Cancer Genome Atlas (TCGA) to assess GFPT1 expression in breast cancer (BRCA) patients." (PMID 39664728, 2024). "Silencing GFPT1 in breast cancer cells reduced viability, induced apoptosis and necrosis, and inhibited migration." (PMID 39664728, 2024). "In conclusion, our study underscores the critical role of GFPT1 in breast cancer progression and metastasis." (PMID 39664728, 2024). "Next, we utilized data from TCGA and GEO to further explore the relationship between GFPT1 expression and survival prognosis in breast cancer patients." (PMID 39664728, 2024). "While previous studies have pointed to GFPT1’s involvement in TNBC and its association with poor prognosis, our findings extend its significance across invasive breast cancer subtypes." (PMID 39664728, 2024). "Given that tumor metastasis involves the migration and invasion of cancer cells, we conducted a transwell migration assay to determine the impact of GFPT1 siRNA and GFPT1 overexpression on breast cancer cell migration." (PMID 39664728, 2024). "In our study, elevated GFPT1 expression was linked to a significantly increased proportion of M2 macrophages, suggesting a direct correlation between GFPT1 expression and the anti-inflammatory infiltration of M2 macrophages in breast cancer tissues." (PMID 39664728, 2024). "To investigate the influence of GFPT1 on apoptosis in breast cancer cells, we employed APC/Annexin V and PI dual-staining flow cytometry to analyze apoptosis and necrosis in human MCF-7 and MDA-MB-231 cells." (PMID 39664728, 2024). "To investigate the role of GFPT1 in breast cancer cell growth, we first employed RNA interference to suppress GFPT1 expression in MCF-7 and MDA-MB-231 cells." (PMID 39664728, 2024). "Targeting GFPT1 may offer new avenues for the treatment of breast cancer, particularly in cases of advanced disease or chemoresistance." (PMID 39664728, 2024).
breast carcinoma (continued). "In summary, our research is the first to identify GFPT1 as a prognostic marker in breast cancer." (PMID 39664728, 2024). "We observed that GFPT1 expression is significantly elevated in breast cancer tissues compared to normal tissues, with a notable correlation between high GFPT1 levels and advanced tumor stages, highlighting its potential role in driving breast cancer progression." (PMID 39664728, 2024). "The expression of GSDMD, a key effector of pyroptosis, was evaluated in MCF-7 and MDA-MB-231 breast cancer cell lines following transfection with GFPT1-targeting siRNA (siRNA-GFPT1#3), an empty vector control (PcDNA3.1), and a GFPT1 overexpression vector (PcDNA3.1 (+)/GFPT1)." (PMID 39664728, 2024). "We also investigated the impact of GFPT1 overexpression on apoptosis in breast cancer." (PMID 39664728, 2024). "Overexpression of GFPT1 significantly increased cell viability in both breast cancer cell lines." (PMID 39664728, 2024). "This regulatory role of GFPT1 in modulating cell viability and apoptosis suggests that targeting GFPT1 could be a promising therapeutic strategy, particularly in metastatic or chemotherapy-resistant breast cancer." (PMID 39664728, 2024). "In terms of clinical significance, our findings suggest that GFPT1 may serve as both a prognostic biomarker and a therapeutic target in breast cancer." (PMID 39664728, 2024). "Importantly, high GFPT1 expression was linked to worse overall survival (OS) rates in both the TCGA-BRCA cohort and independent GEO datasets, establishing GFPT1 as an independent prognostic factor for breast cancer." (PMID 39664728, 2024). "Moreover, bioinformatics analyses revealing GFPT1’s involvement in key oncogenic pathways, including autophagy, nucleotide sugar biosynthesis, and cell cycle regulation, highlight its function as a central regulator of metabolic and proliferative processes in breast cancer cells." (PMID 39664728, 2024). "To explore the immune landscape in breast cancer, we used the ESTIMATE algorithm to assess immune scores, stromal scores, and tumor purity between the GFPT1-Low and GFPT1-High groups in BRCA." (PMID 39664728, 2024). "Our study highlights the clinical relevance of GFPT1, the rate-limiting enzyme in the HBP, in breast cancer." (PMID 39664728, 2024). "We next assessed GFPT1 protein levels and compared its expression in MCF10A cells, derived from normal human mammary epithelial cells, with breast cancer cell lines MCF-7, MB-MDA-231, and T47D." (PMID 39664728, 2024). "Moreover, KEGG pathway enrichment analysis identified several oncogenic pathways enriched in the GFPT1-High group, including the cell cycle, autophagy, nucleotide sugar biosynthesis, AMPK signaling pathway, and Fanconi anemia pathway, involving genes linked to breast cancer susceptibility." (PMID 39664728, 2024). "To further investigate the differences in tumor-infiltrating immune cells (TIICs) between the GFPT1-Low and GFPT1-High groups, we applied the CIBERSORT algorithm to breast cancer patients from the TCGA cohort." (PMID 39664728, 2024). "Similarly, in the GSE42568 dataset, GFPT1 expression was a significant predictor of OS and RFS in breast cancer patients." (PMID 39664728, 2024). "The objective of this study was to explore the potential correlation between GFPT1 expression and survival prognosis in breast cancer (BRCA) patients, investigating how elevated GFPT1 levels may predict poor outcomes." (PMID 39664728, 2024).
pancreatic ductal adenocarcinoma (6 papers, 2013 to 2025). An infiltrating adenocarcinoma that arises from the epithelial cells of the pancreas. "Recently, GFPT1 was found to be overexpressed in pancreatic ductal adenocarcinoma (PDAC) and promoted cancer stemness and metastasis." (PMID 36158580, 2022). "KRAS signaling modulates GFPT1 expression, thereby increasing HBP flux and protein glycosylation in pancreatic ductal adenocarcinoma (PDA) cells." (PMID 40830088, 2025). "In pancreatic ductal adenocarcinoma (PDAC) cells, the hypoxic microenvironment fosters metabolic adaptability and cell survival via HIF-1α-mediated GFPT1 expression." (PMID 40830088, 2025). "Glutamine-fructose-6-phosphate transaminase 1 (GFPT1) is the first rate-limiting enzyme of the hexosamine biosynthesis pathway (HBP), which plays a pivotal role in the progression of pancreatic ductal adenocarcinoma (PDAC)." (PMID 33517899, 2021). "GFPT1 is the rate-limiting enzyme in the HBP and it has been identified as an important contributor to Kras-driven pancreatic ductal adenocarcinoma (PDAC)." (PMID 23724116, 2013). "In lung adenocarcinoma, GFPT2, but not GFPT1, correlates with poor clinical outcomes; however, GFPT1 is required for glycosylation and high expression of GFPT1 predicts poor prognosis in pancreatic ductal adenocarcinoma." (PMID 40740652, 2025).
bladder cancer (5 papers, 2022 to 2025). "In nutrient-deprived TMEs, bladder cancer cells are known to secrete glutamine fructose-6-phosphate transaminase 1 (GFAT1) via sEVs." (PMID 40395335, 2025). "Knockout of the rate-limiting enzyme GFPT1 in HBP metabolism inhibits O-GlcNAcylation, induces ferroptosis, and mitigates chemoresistance of orthotopic bladder cancer in Gfpt1−/− mice." (PMID 40740652, 2025).